C11orf91 (chromosome 11 open reading frame 91)
Tractability: No criterion of Open Targets' tractability assessment is met for any kind of drug.
Gene: Protein-coding gene on chromosome 11 (33,698,261 to 33,700,826, reverse strand). Ensembl gene ENSG00000205177.
Subcellular location (Human Protein Atlas): Vesicles
Genetic constraint (gnomAD): Loss-of-function variants: 8 observed, 10.97 expected, observed/expected ratio (o/e) 0.73, 90% interval 0.43 to 1.31. The synonymous counts are far from expectation, so gnomAD's model fits this gene poorly and the ratio says little. Missense variants: 233 observed, 199.3 expected, observed/expected ratio (o/e) 1.17, 90% interval 1.05 to 1.3. Synonymous variants: 140 observed, 102.76 expected, observed/expected ratio (o/e) 1.36, 90% interval 1.19 to 1.57.
Homologues: Orthologues: chimpanzee CD59 (99% identical), pig C11orf91 (87% identical), dog C11orf91 (85% identical), mouse A930018P22Rik (83% identical), rat C3h11orf91 (83% identical), rabbit C11orf91 (76% identical), guinea pig C11orf91 (68% identical).